CTSV (cathepsin V)
Diseases named in the same sentence as CTSV in open-access papers (continued):
Sharing a sentence is not in itself a finding about the gene and the disease.
thymoma (2 papers, 2020 to 2023). A neoplasm arising from the epithelial cells of the thymus. "The expression of β5t was like that of cathepsin V and was mainly expressed in type B and AB thymomas, compared with type A thymomas and TSCC, and its expression helped to identify TSSC and B3 thymomas." (PMID 36797681, 2023). "Cathepsin V is mainly expressed in cortical thymic epithelial cells (cTECs), and its expression is increased in thymoma patients with myasthenia gravis." (PMID 36797681, 2023). "The expression of β5t, PRSS16, and cathepsin V was higher in type AB and B thymomas than in MNT (p < 0.05)." (PMID 36797681, 2023). "Cathepsin V showed a very unique expression profile with its presence only in type B thymoma and slightly in adjacent tissues." (PMID 31967407, 2020). "Cathepsin V is mainly expressed in type B and AB thymomas, with less expression in A thymomas." (PMID 36797681, 2023). "Our results found that for cortical epithelial markers the expression of β5t, PRSS16, and cathepsin V was higher in type AB and B thymomas than in micronodular thymoma with lymphoid stroma (MNT), and we observed a dramatic increase of β5t and PRSS16 expression in type AB compared to type A thymomas." (PMID 36797681, 2023). "Recently, WHO had suggested a dozen of histochemical markers to differentiate type A and type B thymoma, including TdT, CD1a, CD99, PSMB11 (Beta5T), PRSS16, Cathepsin V, and desmin." (PMID 31967407, 2020). "The combined application of cathepsin V and cathepsin S helped identify TSCC and B3 thymomas." (PMID 36797681, 2023). "Cathepsin V expression was found in 69.6% (16/23) of type B, 69.2% (9/13) of type AB, 40.0% (2/5) of type A thymomas, and 28.6% (2/7) of TSCC, while MNT was not expressed." (PMID 36797681, 2023). "In this study, we aimed to explore the expression of thymic cortical epithelial markers (β5t, PRSS16, and cathepsin V) and medullary epithelial markers (claudin-4, CD40, and AIRE) in thymoma and TSCC and its correlation with histological classification, staging, and prognosis." (PMID 36797681, 2023).
breast ductal carcinoma (1 paper, 2020). "Several studies have demonstrated the overexpression of CTSV in multiple malignant tumours (eg breast ductal carcinoma) and was deemed as a potential prognostic biomarker." (PMID 32649057, 2020).
chondrosarcoma (1 paper, 2025). A malignant cartilaginous matrix-producing mesenchymal neoplasm arising from the bone and soft tissue. "Single-cell RNA sequencing data analysis from GSE184118 indicated that CTSV expression was observed to be activated in conventional central chondrosarcoma patients." (PMID 39897041, 2025). "We provided in vitro and in vivo evidence for the suppressive effect of ugonin V on chondrosarcoma cell motility and metastasis via the stimulation of miR-4799-5p expression, which reduces CTSV synthesis." (PMID 39897041, 2025). "We also found that ugonin V strongly inhibits chondrosarcoma cell motility by regulating CTSV expression." (PMID 39897041, 2025). "To provide additional evidence, we pretreated chondrosarcoma cells with an inhibitor of miR-4799-5p and found that ugonin V via promoting miR-4799-5p suppresses CTSV expression." (PMID 39897041, 2025). "Collectively, these findings provide evidence of the remarkable expression of CTSV in patients with chondrosarcoma." (PMID 39897041, 2025). "We provided evidence for CTSV detection using bioinformatics analysis, qPCR analysis, and IHC staining to indicate the remarkably higher expression of CTSV in chondrosarcomas." (PMID 39897041, 2025). "This study aimed to investigate the effect of ugonin V on chondrosarcoma metastasis through the inhibition of CTSV expression mediated by miR-4799-5p." (PMID 39897041, 2025). "Therefore, miR-4799-5p acts as a mediator of the ugonin V-induced suppression of CTSV expression and chondrosarcoma metastasis." (PMID 39897041, 2025). "Therefore, ugonin V suppressed CTSV and chondrosarcoma cell motility by promoting miR-4799-5p directed binding to the CTSV 3ʹ-UTR." (PMID 39897041, 2025). "Interestingly, CTSV expression was significantly higher in high-grade chondrosarcomas than in low-grade chondrosarcomas." (PMID 39897041, 2025). "In addition, through miRNA sequencing, we observed that ugonin V targets CTSV via miR-4799-5p to effectively suppress chondrosarcoma cell migration and invasion." (PMID 39897041, 2025). "Hence, it is essential to further investigate the correlation between cathepsin V levels and chondrosarcoma." (PMID 39897041, 2025). "Therefore, ugonin V demonstrates an inhibitory effect on the regulation of chondrosarcoma cell migration and invasion via CTSV suppression." (PMID 39897041, 2025). "In addition, whether ugonin V induces stimulation of another miRNA target, CTSV, and chondrosarcoma cell migration and invasion remain to be determined by further research." (PMID 39897041, 2025). "However, the role of cathepsin V in the progression of chondrosarcoma remains unclear." (PMID 39897041, 2025). "Moreover, miR-4799-5p was demonstrated to directly bind to CTSV 3'-UTR to suppress CTSV synthesis and then inhibit chondrosarcoma cell migration and invasion in ugonin V treatment." (PMID 39897041, 2025). "Analysis of the GSE30835 dataset, which consists of chondrosarcoma tissues and normal cartilage, revealed significant upregulation of three cathepsin proteases in chondrosarcoma, namely cathepsin (CTS) A, L, and V. Notably, ugonin V specifically suppressed cathepsin V mRNA expression." (PMID 39897041, 2025). "We then examined the mRNA expression levels of CTSV in the tissues of patients with chondrosarcoma and noncancerous cartilage from osteoarthritis (OA) patients." (PMID 39897041, 2025).
delirium (1 paper, 2023). A disorder characterized by confusion; inattentiveness; disorientation; illusions; hallucinations; agitation; and in some instances autonomic nervous system overactivity. "We observe decreased levels in three proteases (CTSV, CTSD and MMP14) in the CSF of patients that will develop delirium." (PMID 37759795, 2023).
fibrosarcoma (1 paper, 2020). A malignant mesenchymal fibroblastic neoplasm affecting the soft tissue and bone. "The significance of N-glycosylation for the transport of cathepsin V was studied in human fibrosarcoma cells, where mutational elimination of one or two N-glycosylation sites led to decreased secretion rates, while also affecting the sorting of the mutant cathepsin V forms to endo-lysosomes." (PMID 33266306, 2020).
Hepatic fibrosis (1 paper, 2024). The presence of excessive fibrous connective tissue in the liver. "Transplantation of HBOs could promote the high expression of CTSV in hepatic sinusoid endothelial cells, which might halt the progression of hepatic sinusoidal capillarization and liver fibrosis." (PMID 38385067, 2024). "The high expression of MMP family genes may contribute to the ectopic homing and in situ residence of HBOs, and more importantly, the CK19-positive labeling of a new ductular reaction pattern and the high expression of cathepsin V (CTSV) may serve as potential therapeutic targets for liver fibrosis." (PMID 38385067, 2024). "The high expression of CTSV in LSECs following HBO transplantation may help to slow the development of hepatic sinusoidal capillarization and liver fibrosis, as was discovered for the first time in our work." (PMID 38385067, 2024).
hyperhomocysteinemia (1 paper, 2022). A serious metabolic condition caused by mutations in the MTHFR gene, medications, or nutritional deficiency. "Indeed, Anti-CTSV treatment has anti-inflammation effect in the thoracic aorta of hyperhomocysteinemia mice." (PMID 35443863, 2022).
lung diseases (1 paper, 2022). "On the other hand, ADAM33 interacts with CTSK and CTSV genes, phagosomal cathepsin genes, being related to lung diseases." (PMID 36411793, 2022).
neuroblastoma (1 paper, 2018). Neuroblastoma (NB) is the most common solid, extracranial childhood tumor. "Processing of proenkephalin and pro-NPY precursors by cathepsin V has been demonstrated in human neuroblastoma cells in vitro." (PMID 29998195, 2018). "Gene silencing of cathepsin V reduces production of enkephalin by more than 80% in human neuroblastoma cells, and expression of cathepsin V increases production of enkephalin and NPY." (PMID 29998195, 2018).
oral cancer (1 paper, 2019). "Western blot and immunofluorescence results indicated that ADAM9, cathepsin V and kallikrein 5 were expressed at high levels in oral cancer cell lines." (PMID 30602733, 2019).
pancreatic cancer (1 paper, 2025). "Our integrative single-cell and bulk-RNA workflow identifies ANLN, NT5E, and CTSV as novel prognostic biomarkers in pancreatic cancer and highlights a pro-tumorigenic interaction between malignant ductal cells and macrophages." (PMID 40666516, 2025). "Finally, in vitro knockdown of CTSV assessed its functional role in pancreatic cancer (PAC) cell proliferation and migration." (PMID 40666516, 2025).
prostatitis (1 paper, 2024). An infectious or non-infectious inflammatory process affecting the prostate gland. "In reverse MR, we found an association between genetically predicted prostatitis and cathepsin V levels by utilizing 15 prostatitis-related SNPs." (PMID 38904040, 2024). "Using IVW methods, there is a decrease in the expression of cathepsin V in prostatitis cases (OR=0.89, 95% CI=0.80–0.99, p-value=0.0349)." (PMID 38904040, 2024). "Additionally, prostatitis negatively affected cathepsin V level." (PMID 38904040, 2024). "Through reverse MR analysis, it was revealed that prostatitis had an adverse impact on cathepsin V (IVW OR=0.89, 95% CI 0.80–0.99, P=0.035), while no favorable association was observed between BPH and cathepsins." (PMID 38904040, 2024).
sickle cell disease (1 paper, 2012). Sickle cell anemias are chronic hemolytic diseases that may induce three types of acute accidents: severe anemia, severe bacterial infections, and ischemic vasoocclusive accidents (VOA) caused by sickle-shaped red blood cells obstructing small blood vessels and capillaries. "There is a pressing need for novel pharmaceutical targets to inhibit these activities, and from this work, we propose that JNK, cathepsin K, and cathepsin V are three new targets for inhibition to reduce pathological arterial remodeling in sickle cell disease." (PMID 22550569, 2012).
thymic tumors (1 paper, 2023). "In conclusion, our findings, for the first time, estimated the expression of thymic cortical (β5t, PRSS16, and cathepsin V) and medullary epithelial markers (AIRE, CD40, and claudin-4) in differential diagnosis, Masaoka-Koga stage, histological classification, and prognosis of thymic tumors." (PMID 36797681, 2023).
transitional cell carcinoma (1 paper, 2021). A malignant neoplasm arising from the transitional epithelium, usually affecting the urinary bladder, ureter, or renal pelvis. "Irrespective of the tumor type, CDC20 and CTSV showed higher expression in transitional cell carcinoma." (PMID 34885040, 2021).
tumor (33 papers, 2015 to 2026). "Recent research has further elucidated CTSV’s role in regulating cell cycle progression and proliferation, demonstrating its association with poor prognosis and tumor microenvironment modulation in HCC." (PMID 40269756, 2025). "More importantly, the reduction in tumorigenic potential caused by CTSV deficiency was witnessed in vivo, evidenced by smaller tumor size and weight in mice bearing CTSV-deficient T24 cells compared with the control groups." (PMID 35443863, 2022). "Higher cathepsin V levels were associated with increasing tumor stage, distant metastases, and lower patient survival." (PMID 36147668, 2022). "Previous studies have shown that CTSV is primarily expressed in the stromal tissue surrounding PDAC tumor cells, and its elevated expression is associated with poor prognosis in PDAC patients, making it a potential biomarker and treatment target for prognostic assessment." (PMID 38493095, 2024). "Elevated CTSV expression has been observed in numerous cancer types, including squamous cell, breast, colorectal and thymic epithelial malignancies, and associated with increasing tumour grade/stage in hepatocellular and endometrial malignancies." (PMID 38026973, 2023). "The tumor repression resulting from CTSV deficiency in vitro was also verified in vivo." (PMID 35443863, 2022). "Given the AUC value, salivary MLT could present a satisfactory diagnostic tool for OSCC as a tumour biomarker alone or in along with some other molecules, such as kininogen 1, cathepsin V, kallikrein 5 or matrix metalloproteinase 146–48." (PMID 34168230, 2021). "Given that elevated CTSV expression was associated with reduced survival in ER-positive tumours, we wanted to determine if CTSV may represent a future therapeutic target in this subtype of the disease." (PMID 33298139, 2020). "The natural flavonoid compound Ugonin V has been shown to regulate miR-4799-5p, leading to downregulation of cathepsin V (CTSV), a cysteine protease implicated in tumor progression." (PMID 40429954, 2025). "Elevated expression of CTSV was correlated with OS event, residual tumor, Pathologic stage, N stage, T stage, and M stage." (PMID 38078882, 2023). "Depletion of CTSV enhanced T cell activity and contributed to the anti-tumor impact, as demonstrated by co-culturing A549 and NCI-H1975 cells with PBMCs." (PMID 38078882, 2023). "In this study we have identified that CTSV depletion attenuates tumour cell proliferation, by mediating a delay in cell cycle progression." (PMID 38026973, 2023). "Examination of the molecular role of the protease within Luminal A tumours, revealed that CTSV promotes tumour cell invasion and proliferation, in addition to degradation of the luminal transcription factor, GATA3, via the proteasome." (PMID 38026973, 2023). "We created an antibody that specifically targets CTSV and successfully blocks its ability to cleave fibronectin, E-cadherin, and N-cadherin, which reduces tumor cell invasion and migration." (PMID 38078882, 2023). "Taken together, we have identified and characterized novel, potent, selective inhibitors of cathepsin V that interfere with processes of tumor progression in which cathepsin V is involved." (PMID 36147668, 2022). "We further evaluated the effects of the most potent selective reversible cathepsin V inhibitor, compound 7, on tumor cell proliferation using CFSE-labeled MCF7 cells." (PMID 36147668, 2022). "For this, we developed cell-based in vitro functional assays to simulate processes in which cathepsin V is known to play an important role: elastin degradation, tumor cell proliferation, and immune cell cytotoxicity." (PMID 36147668, 2022). "Cathepsin V (CTSV/CTSL2) is a proteolytic enzyme that degrades the extracellular matrix promoting tumor metastasis and invasion." (PMID 35480307, 2022).
tumor (continued). "Evidence has shown that cysteine cathepsins including CTSV can be secreted from tumour cells, and recent publications have identified ectodomain shedding is undertaken by cathepsin family members to influence intracellular signalling pathways." (PMID 33298139, 2020). "Although these studies have discovered CTSV and CTSC involved in tumor progression, the intracellular signaling cascades linking the Pra-B regulate the levels of CTSV and CTSC in RCC cells for further investigation." (PMID 32331211, 2020). "As expected, CTSV silencing by shRNA led to significantly reduced tumour cell invasion compared to NTC cells." (PMID 33298139, 2020). "We have identified that CTSV promotes ER-positive breast cancer through facilitating tumour cell proliferation, invasion and suppressing the expression of GATA3." (PMID 33298139, 2020). "Research has also identified that cathepsin V expression is elevated in tumour tissues from numerous other malignancies, but despite this, there has been limited examination of the function of this protease in cancer." (PMID 33298139, 2020). "In PAC, CTSV may enhance tumor cell migration and invasion by promoting extracellular matrix degradation and remodeling." (PMID 40666516, 2025). "Several studies have suggested that cathepsin V contributes to tumor cell hyperproliferation." (PMID 36147668, 2022). "In view of this, we evaluated the effect of cathepsin V inhibition on tumor cell proliferation." (PMID 36147668, 2022). "Kallikrein 5, cathepsin V and ADAM9were expressed at a higher level in all tumor cell lines." (PMID 30602733, 2019). "In the next step, we prepared tumor spheroids from NCH-421k cells and exposed them to NK cells from healthy donors and cathepsin V inhibitor under static conditions." (PMID 41229419, 2025). "In the co-culture assay, CTSV overexpression consistently reduces caspase 3/7 cleavage and caspase 3/7 activity in A549 and NCI-H1975 cells while favoring tumor immune escape." (PMID 38078882, 2023). "TIMER database analysis confirmed that CTSV and MKI67 were highly expressed in tumour tissues, while CXCL8 and PRF1 were expressed at low levels in tumour tissues, which was consistent with our findings." (PMID 35902905, 2022). "ITGA8 and ADAMTS8 were downregulated in tumor tissues, whereas FERMT1, CTSV, CPS1, ENTPD2, SERPINB5, and LYPD3 were upregulated in tumor tissues." (PMID 35557945, 2022). "Univariate analysis of gene expression data on tumor aggressiveness (NMIBC versus MIBC) using logistic regression showed genes, including CDKN2A, CTSV, FOXM1, and KRT23, were predictive of tumor aggressiveness." (PMID 34885040, 2021). "The results of univariate analysis demonstrate that CDKN2A, CTSV, FOXM1 and KRT23 were predictive of tumor aggressiveness (MIBC) and the odds of having MIBC was increased by 3% per unit increase of CDKN2Aa (p = 0.01)." (PMID 34885040, 2021). "CtsV is not expressed in mouse, thus limiting our understanding of its potential role in the onset and progression of human tumours." (PMID 39851495, 2025). "This confirms that cathepsin V plays a role in tumor cell proliferation, whereas cathepsins L and S do not." (PMID 36147668, 2022). "Moreover, the results of q-RT PCR showed that CTSV, RGS4, SYT13 and NPTX1 were highly expressed in tumor tissues compared with adjacent tumor tissues, while SLC25A15, ENTPD2 and CA8 were low expressed." (PMID 36684237, 2022). "The acidosis-related signature is composed of seven key genes (ARNTL2, DKK1, CEP55, CTSV, MYEOV, DSG2, and GBP2), all of which have elevated expression levels in PC tumor tissues compared with normal tissues and are all related to adverse clinical outcomes in patients with PC." (PMID 34993253, 2021).